GLYAT (glycine-N-acyltransferase)
Description:
Mitochondrial acyltransferase which transfers an acyl group to the N-terminus of glycine and glutamine, although much less efficiently. Can conjugate numerous substrates to form a variety of N-acylglycines, with a preference for benzoyl-CoA over phenylacetyl-CoA as acyl donors. Thereby detoxify xenobiotics, such as benzoic acid or salicylic acid, and endogenous organic acids, such as isovaleric acid.
Synonyms: ACGNAT; GAT
Tractability: PROTAC: its protein half-life has been measured.
Gene: Protein-coding gene on chromosome 11 (58,640,426 to 58,731,974, reverse strand). Ensembl gene ENSG00000149124.
Subcellular location: Mitochondrion
Pathways (Reactome):
Metabolism: Branched-chain amino acid catabolism; Conjugation of benzoate with glycine; Conjugation of carboxylic acids; Conjugation of salicylate with glycine
Drug ADME: Aspirin ADME
Gene Ontology:
Molecular function: glycine N-acyltransferase activity; glycine N-benzoyltransferase activity; protein binding; acyltransferase activity
Biological process: benzoyl-CoA metabolic process; glycine metabolic process; acyl-CoA metabolic process; branched-chain amino acid catabolic process; monocarboxylic acid metabolic process; response to toxic substance; xenobiotic metabolic process
Cellular component: mitochondrion; mitochondrial matrix
Genetic constraint (gnomAD): Loss-of-function variants: 7 observed, 5.05 expected, observed/expected ratio (o/e) 1.38, 90% interval 0.75 to 1.91. That is too few expected variants to judge how well the gene tolerates losing a copy. Missense variants: 229 observed, 207.25 expected, observed/expected ratio (o/e) 1.11, 90% interval 0.99 to 1.23. Synonymous variants: 76 observed, 70.22 expected, observed/expected ratio (o/e) 1.08, 90% interval 0.9 to 1.31.
Homologues: Orthologues: chimpanzee GLYAT (99% identical), macaque GLYAT (93% identical), pig GLYAT (75% identical), dog GLYAT (74% identical), rat Glyat (74% identical), guinea pig GLYAT (73% identical), mouse Glyat (73% identical), rabbit GLYAT (58% identical), tropical clawed frog glyatl2 (31% identical), zebrafish si:ch73-106k19.2 (24% identical), zebrafish si:dkey-76k16.6 (23% identical), Caenorhabditis elegans ZK185.3 (22% identical), and 3 more. Paralogues in human: GLYATL2 (41% identical), GLYATL1B (40% identical), GLYATL1 (39% identical), GLYATL3 (33% identical).
Diseases named in the same sentence as GLYAT in open-access papers:
GLYAT is named in the same sentence as 23 diseases in open-access papers, as found by Europe PMC text mining. Sharing a sentence is not in itself a finding about the gene and the disease. The quoted sentences say what the papers report.
breast carcinoma (6 papers, 2021 to 2025). "Studies have linked GLYAT dysregulation to tumour growth and metastasis in breast cancer via activation of the PI3K/AKT/Snail pathway." (PMID 39495775, 2024). "GLYAT converts glycine to acyl glycine, and lower expression is correlated with poor overall survival of breast cancer patients." (PMID 40426890, 2025). "Prior research has demonstrated that the downregulation of GLYAT enhances invasion, migration and proliferation of breast cancer cells by modulating epithelial‐mesenchymal transition (EMT), a finding validated in animal models." (PMID 39495775, 2024). "While prior research has shed light on the importance of GLYAT in malignancies such as breast cancer and hepatocellular carcinoma, its role in the pathophysiology of KIRC remains an underexplored frontier." (PMID 38066746, 2023). "Reduced levels of glycine N-acyltransferase have been reported in human breast cancer metastasis and progression." (PMID 36295878, 2022). "Our series of experiments found that human breast cancer cells and tissues contained remarkably suppressed levels of GLYAT." (PMID 33968740, 2021). "In conclusion, our study is the first of its kind to implicate GLYAT to be a breast cancer anti-oncogene." (PMID 33968740, 2021). "We further demonstrated that GLYAT regulates breast cancer migration and invasion via EMT modulation." (PMID 33968740, 2021). "Nevertheless, literature is scarce surrounding GLYAT expression and its impact on human breast cancer." (PMID 33968740, 2021). "In vitro assays were carried out in MDA-MB-231 cells with GLYAT knockdown (KD) and overexpression (OE) in MCF-7 cells to determine the impact of GLYAT expression on breast cancer behavior." (PMID 33968740, 2021). "Immunohistochemical experiments found that breast cancer tissues possessed markedly decreased GLYAT expression in contrast to healthy breast tissue." (PMID 33968740, 2021). "The current investigation uncovered markedly suppressed GLYAT expression in breast cancer cells and tissues, which correlated with poorer prognosis and highly malignant clinicopathologic features in individuals with breast cancer." (PMID 33968740, 2021). "Our findings demonstrate that downregulation of GLYAT expression in human breast cancer is correlated with EMT via the PI3K/AKT/Snail pathway and is also associated with histological grade, tumor TNM stage, Ki-67 status, and poor survival in breast cancer patients." (PMID 33968740, 2021). "A Kaplan-Meier analysis from GEPIA dataset and a scatter plot from the Human Protein Atlas dataset suggested that patients with low GLYAT expression in breast cancer tissues had worse overall survival (OS), further highlighting the suppressive function of GLYAT in BC progression." (PMID 33968740, 2021). "Interestingly, the EMT pathway appeared to be inhibited in the presence of GLYAT, working to decrease in vivo and in vitro breast cancer cell migration through alteration of the PI3K/ATK/Snail signaling pathway." (PMID 33968740, 2021). "We therefore hypothesized that GLYAT might suppress breast cancer metastasis by modulation of this pathway." (PMID 33968740, 2021). "Additionally, analysis of data published in another study in Nature which compared mRNA expression levels of GLYAT in normal breast tissues with invasive ductal and invasive lobular carcinoma revealed that two breast carcinoma subtypes had lower GLYAT mRNA levels." (PMID 33968740, 2021). "However, the expression of GLYAT was not statistically significant change in other cancer types, besides BRCA, LIHC and CHOL, which indicated that GLYAT may have specific function in breast cancer." (PMID 33968740, 2021). "GLYAT may act in combination with ER or PR status to impact breast cancer prognosis." (PMID 33968740, 2021).
hepatocellular carcinoma (6 papers, 2020 to 2024). A malignant tumor that arises from hepatocytes. "In the case of glycine conjugation, it has been shown that GLYAT expression is transcriptionally down-regulated in hepatocellular carcinoma specimens." (PMID 33803916, 2021). "Previous reports shown that GLYAT expression is suppressed in hepatocellular carcinoma and GLYAT is involved in the development of musculoskeletal development." (PMID 33177615, 2020). "Studies have shown that GLYAT expression is suppressed in human hepatocellular carcinomas and may be a critical molecule in the transition between the differentiation and carcinogenesis of liver cells." (PMID 33968740, 2021). "Hence, GLYAT emerges as a pivotal target gene influencing HCC progression, with increased GLYAT expression potentially attenuating the malignancy of hepatocellular carcinoma." (PMID 39495775, 2024).
Obesity (3 papers, 2019 to 2023). Accumulation of substantial excess body fat. "This evidence points towards a role of adipose GLYAT and secreted acylglycines in the development of an adipose-resistant phenotype in an in vivo mice model of obesity, similar to the results observed in our in vitro human model." (PMID 36005620, 2022). "GLYAT overexpression has been observed in the adipose tissue of obesity-resistant mice compared to mice that develop obesity in response to a high-fat diet, together with increased urinary excretion of isovalerylglycine and hexanoylglycine." (PMID 36005620, 2022). "The perturbation of GLYAT induces harmful disruption to CoA homeostasis, musculoskeletal development, and obesity-related metabolic disturbances, suggesting that acetylglycine plays a role in the development of obesity-related diseases." (PMID 37122566, 2023).
asthma (1 paper, 2022). "However, there have been no reports on the pathogenesis of the GLYAT gene in asthma and other diseases." (PMID 36463267, 2022).
developmental delays (1 paper, 2025). "This case identifies a novel homozygous nonsense variant in the GLYAT, leading to glycine N‐acyltransferase enzyme deficiency and associated developmental delays." (PMID 40747359, 2025). "We present a novel case of GLYAT enzyme deficiency in a patient with developmental delay, autistic features, and locomotor dysfunction." (PMID 40747359, 2025).
Glycinuria (1 paper, 2025). "Glycinuria was due to different mechanisms, including the overflow resulting from the high plasma glycine levels, high activity of the GLYAT enzyme in the kidney, as well as the renal defect that occurred in the patient, which might be due to the toxic accumulation of GLYAT substrates." (PMID 40747359, 2025).
liver cancer (1 paper, 2023). An epithelial or non-epithelial malignant neoplasm that arises from the liver. "On the basis of the expression of the newly edited and generated ED_miR-3144(3_A < G) target gene was reduced as liver cancer progressed, five candidates, INMT, GHR, GLYAT, SLC38A4, and HMGCS2, were identified through target prediction and expression pattern analyses." (PMID 36599932, 2023).
cancer (8 papers, 2018 to 2025). A tumor composed of atypical neoplastic, often pleomorphic cells that invade other tissues. "Glycine N‐acyltransferase (GLYAT), known to influence glycine metabolism, has been implicated in the progression of various malignant tumours." (PMID 39495775, 2024). "Given that metabolic pathway aberrations are a hallmark of cancer, and considering the observed downregulation of GLYAT in other malignancies, our study focuses on assessing GLYAT expression levels in KIRC cases." (PMID 38066746, 2023). "In particular, downregulation of GLYAT expression is associated with a variety of malignant tumors, including BC tumors." (PMID 37024893, 2023). "Aberrant GLYAT expression is associated with human cancers, yet its role in cancer remains unknown." (PMID 35933447, 2022). "Glycine N-acyltransferase (GLYAT; EC 2.3.1.13, Accession ID: AAI12537) is a key enzyme in mammalian homeostasis that has been linked to several pathologies in humans, including cancer." (PMID 40938199, 2025). "Collectively, our analyses reveal that GLYAT displays elevated expression in hepatic and renal tissues, while its expression is downregulated in cancer samples." (PMID 38066746, 2023). "The GLYAT methylation level analysis showed a consistent trend of hypomethylation in various cancer types relative to normal tissue, suggesting a shared role for this epigenetic modification of the GLYAT gene in tumor cells." (PMID 38066746, 2023). "In this context, our research focused on glycine N-acyltransferase (GLYAT), an enzyme known to play a role in various metabolic diseases and cancer." (PMID 38066746, 2023). "In summary, the data shown here suggest that GLYAT appears to play a multifaceted role in cancer, particularly in KIRC." (PMID 38066746, 2023). "In fact, GLYAT downregulation has been observed in various cancer types, suggesting a potential tumor suppressor role." (PMID 38066746, 2023). "This Web tool corroborated the downregulation of GLYAT in a majority of the cancers highlighted by TIMER2.0." (PMID 38066746, 2023). "GLYAT expression was determined by immune blot and immunohistochemistry in three BC cell lines and primary cancer tissues." (PMID 33968740, 2021). "Specialized in the biochemical conjugation of xenobiotics like benzoic acid with the amino acid glycine, GLYAT is more than a mere metabolic workhorse; it also serves as a key modulator of glycine availability, an aspect of singular relevance in cancer physiology." (PMID 38066746, 2023). "It would be worth investigating whether GLYAT has a role in stromal-to-tumor signaling pathways, potentially impacting cancer cell metabolism, growth, or invasion." (PMID 38066746, 2023). "In particular, the role of GLYAT in mitigating glycine absorption or biosynthesis can have downstream implications on cancer cell growth, likely by hindering the synthesis of nucleic acids, thus disrupting a key metabolic dependency of rapidly proliferating cancer cells." (PMID 38066746, 2023). "All the algorithms used in this analysis (EPIC, MCP-counter, EXCELL, and TIDE) showed that a consistent negative correlation exists between the expression of the GLYAT gene and the levels of cancer-associated fibroblasts (CAF) in KIRC." (PMID 38066746, 2023). "This suggests that the downregulation of GLYAT is a common feature in cancer." (PMID 38066746, 2023). "The negative correlation between GLYAT expression and levels of cancer-associated fibroblasts (CAFs) invites speculation as to whether GLYAT may have an inhibitory role on CAFs or is downregulated in response to signals from CAFs." (PMID 38066746, 2023). "Additionally, we observed a hypomethylation in the GLYAT promoter region and a negative correlation between the expression of the GLYAT and the levels of cancer-associated fibroblasts." (PMID 38066746, 2023).
cancer (continued). "Furthermore, given that GLYAT expression was primarily co-localized to stromal cells in the tumor microenvironment, one must consider the possible interplay between GLYAT and stromal cells in cancer progression." (PMID 38066746, 2023). "The observed downregulation of GLYAT in KIRC and other cancer types is notable, particularly given its pronounced baseline expression in renal and hepatic tissues." (PMID 38066746, 2023).
tumor (7 papers, 2018 to 2025). "Subsequent investigations revealed associations between GLYAT expression and the tumour immune microenvironment, as well as immunotherapy sensitivity." (PMID 39495775, 2024). "Delving into the specific contributions of GLYAT to the biology of KIRC may drive underlying mechanistic pathways that contribute to the tumor’s development, aggressiveness, and resistance to current therapies." (PMID 38066746, 2023). "We employed two methods, CIBERSORT and ESTIMATE, to assess immune cell infiltration and explore the interaction between GLYAT expression and the tumour immune microenvironment." (PMID 39495775, 2024). "Considering the distinct tumour immune microenvironment in groups with low and high GLYAT expression, we conducted IPS analysis to assess the potential responsiveness to immunotherapy targeting PD‐1 and CTLA‐4." (PMID 39495775, 2024). "Taking this into account, we further characterized the GLYAT gene expression in the tumor microenvironment at a single-cell resolution by using the TISCH Web tool." (PMID 38066746, 2023). "Future studies should investigate GLYAT’s metabolic functions, epigenetic regulation, role in the tumor microenvironment, and impact on disease progression and patient survival to elucidate its precise role in KIRC tumorigenesis and progression." (PMID 38066746, 2023). "Building upon this, we investigated the dynamics of GLYAT protein levels in different tumor grades and at different KIRC stages, using different public databases." (PMID 38066746, 2023). "In summary, our analysis revealed a consistent trend of GLYAT gene hypomethylation in different tumor types, suggesting a possible conserved role." (PMID 38066746, 2023). "Here, the data showed a statically significant downregulation of GLYAT in both tumor and metastatic cells." (PMID 38066746, 2023). "IHC analysis indicated that GLYAT was decreased in human BC tissues and lower GLYAT expression was correlated with histological grade, tumor TNM stage, Ki-67 status, and poorer survival in BC patients." (PMID 33968740, 2021). "Furthermore, in vitro functional experiments demonstrated that low GLYAT expression markedly promoted the malignant behaviour of tumour cells." (PMID 39495775, 2024). "Decreased GLYAT activity may lead to metabolic changes that promote tumor growth and KIRC progression." (PMID 38066746, 2023). "Additionally, these studies should include larger and more detailed clinical information, as well as functional studies to assess the role of GLYAT in tumor cell proliferation, migration, and survival." (PMID 38066746, 2023). "Furthermore, the data show that GLYAT is conserved at basal levels in the tumor microenvironment of KIRC cells." (PMID 38066746, 2023). "Given the prominent role of EMT in tumor spread, we postulated that GLYAT may be involved in the EMT process." (PMID 33968740, 2021). "Besides the impact on metastasis, the proliferation ability of BC cells was increased after inhibiting GLYAT both in vitro and in vivo, further highlighting the tumor suppressed role of GLYAT." (PMID 33968740, 2021). "The role of GLYAT in tumor growth and metastasis was also assessed in nude mice in vivo." (PMID 33968740, 2021). "Results revealed that GLYAT overexpression significantly inhibited the proliferation, invasion and migration of hepatocellular cell lines, suggesting a potential role in mitigating tumour recurrence, metastasis and poor prognosis, in line with previous findings." (PMID 39495775, 2024). "Given that the poor prognosis of HCC is often attributed to early tumour metastasis and recurrence, with EMT playing a crucial role in intra‐ and extrahepatic metastasis, we delved into GLYAT's role in HCC through in vitro experiments." (PMID 39495775, 2024).
tumor (continued). "Subsequently, using the CIBERSORT algorithm, we found positive correlations between GLYAT expression and mast cells resting, monocytes, macrophages M2, macrophages M1, T cell CD4 naive and NK cells activated in the tumour immune microenvironment." (PMID 39495775, 2024). "To evaluate the GLYAT expression level in neoplastic tissues, we utilized the TIMER2.0 resource, contrasting the mRNA expression profiles of GLYAT between tumor specimens and their corresponding normal samples." (PMID 38066746, 2023). "Our research is the only study to illustrate the role of GLYAT in BC patients, revealing that down-regulated GLYAT induces EMT and tumor metastasis via PI3K/AKT/Snail signaling." (PMID 33968740, 2021). "The consistency in the downregulation of GLYAT across different tumor grades and stages in KIRC without a relation to differentiation raises significant clinical questions." (PMID 38066746, 2023). "The analysis showed a marked decrease in GLYAT expression in all stages and grades of KIRC, regardless of mutation rates, suggesting an alternative mechanism of regulation along the tumor development." (PMID 38066746, 2023). "Moreover, given GLYAT’s known role in cell growth and migration, its downregulation in KIRC tumors may contribute to tumor progression." (PMID 38066746, 2023). "The widespread downregulation of GLYAT in KIRC tumors, regardless of grade or stage, suggests its involvement in early tumor development and as a potential marker of tumor aggressiveness." (PMID 38066746, 2023).
metabolic disease (1 paper, 2023). A congenital disorder (due to inherited enzyme abnormality) or acquired (due to failure of a metabolically important organ) disorder resulting from an abnormal metabolic process. "Glycine N-acyltransferase (GLYAT) is an enzyme that has recently attracted interest in the pathophysiological mechanisms of metabolic diseases." (PMID 38066746, 2023).
GLYAT also shares sentences with these, for which no sentence is quoted: melanoma (2 papers); bladder cancer (1); cholangiocarcinoma (1); colon adenocarcinoma (1); head and neck squamous cell carcinoma (1); invasive lobular carcinoma (1); kidney (1); kidney cancer (1); lung adenocarcinoma (1); lung squamous cell carcinoma (1); rectum adenocarcinoma (1); renal adenocarcinoma (1); thyroid carcinoma (1).